TRIM21 (tripartite motif containing 21)
Diseases named in the same sentence as TRIM21 in open-access papers (continued):
Sharing a sentence is not in itself a finding about the gene and the disease.
systemic lupus erythematosus (continued). "In this study, we generated and analyzed MRL/lpr lupus-prone mice in which Trim21 gene is deleted to investigate the function of TRIM21 in autoimmune pathogenesis." (PMID 32117252, 2020). "MRL/lpr mice, which are model mice spontaneously developing lupus-like symptoms, including anti-TRIM21 Ab production, expressed the transcript of Trim21 ubiquitously as shown in the previous study using C57BL/6 mice." (PMID 32117252, 2020). "Flow cytometric analyses showed that B cells were significantly increased in the spleens and sdLNs by Trim21 gene disruption in lupus-prone mice." (PMID 32117252, 2020). "The activation of TRIM21 by leaked immune complexes in lysosome-maturation-defective macrophages of lupus-prone mice illustrates the consequences of such an event." (PMID 29667579, 2018). "By contrast, TRIM21 overexpression attenuated autoimmunity in lupus-prone mice." (PMID 40610751, 2025). "TRIM21 deficiency induced exaggerated lupus-mimicking phenotypes and increased IFN production along with an activated STING pathway in both induced and spontaneous murine lupus." (PMID 40610751, 2025). "Considering the decreased TRIM21 expression in lupus-prone mice, we wished to determine whether TRIM21 overexpression by in vivo gene therapy could ameliorate lupus-like phenotypes in MRL/lpr mice." (PMID 40610751, 2025). "Therefore, it is certain that the Trim21 gene deletion has an impact on nephritis and autoantibody production in lupus pathogenesis." (PMID 32117252, 2020). "After local damage induction by ear tagging, Ro52/TRIM21−/− mice develop a lupus-like phenotype." (PMID 26137972, 2015). "Interestingly, the striking difference in the phenotype of 2 Ro52/Trim21-KO mice, in which one develops lupus-like disease and the other has a normal life span, has been attributed to the potential production of a truncated Ro52 protein that is overexpressed in the mouse that develops lupus." (PMID 36040804, 2022). "TRIM21 previously known as an autoantigen involved in several autoimmune diseases, e.g., systemic lupus erythematosus (SLE)." (PMID 25368619, 2014). "Here, we report that TRIM21 ubiquitinates and degrades STING, thereby limiting the production of type I IFN and induced or spontaneous lupus-related pathology in mice." (PMID 40610751, 2025). "In the present study, we have shown that TRIM21 regulates the pathological production of type I IFN in murine and human lupus by directly interacting with STING." (PMID 40610751, 2025). "Although autoantibodies against TRIM21 are frequently detected in patients with systemic lupus erythematosus (SLE), its role in disease pathogenesis remains unclear." (PMID 40610751, 2025). "TRIM21 (known as Ro52), an autoantigen in patients with SLE (systemic lupus erythematosus), targets DDX41 for degradation." (PMID 33670221, 2021). "Next, we evaluated whether expression levels of TRIM21 and STING, directly correlate with each other in the lupus-prone mice." (PMID 40610751, 2025). "Researches indicate that T cells and DCs contribute to the activation and diversification of B cells, but in lupus mouse models, the absence of TRIM21 did not alter the status of T cells and DCs, due to the abnormal function of B cells themselves." (PMID 39165359, 2024). "For example, it will be interesting to investigate whether disease severity of murine lupus model strains, such as MRL/lpr, BWF1, and B6-Yaa, can be diminished by adenovirus-mediated Trim21 gene transfer." (PMID 22701487, 2012). "They found that mice lacking TRIM21 had more severe lupus symptoms and higher levels of IFNs." (PMID 40610751, 2025). "This has been demonstrated in lysosome-maturation impaired macrophages from lupus-prone mice, in which leakage of IgG containing immune complexes from the endosomal pathway into the cytosol triggers a TRIM21 dependent inflammatory response in the absence of infection." (PMID 31555278, 2019).
systemic lupus erythematosus (continued). "TRIM21 (Ro52/SSA1) is a member of the TRIM (Tripartite Motif) family of single-protein E3 ligases and was originally identified as an autoantigen prevalent in Systemic Lupus Erythematosus (SLE)." (PMID 22479513, 2012).
autoimmune disease (97 papers, 2009 to 2025). A disorder resulting from loss of function or tissue destruction of an organ or multiple organs, arising from humoral or cellular immune responses of the individual to their own tissue constituents. "TRIM21 is a cytosolic E3 ubiquitin ligase that was initially described as an autoantigen in autoimmune diseases and later associated with the intracellular antiviral response." (PMID 36982215, 2023). "The interconnected role of TRIM21/Ro52 in regulating autoimmunity and cell metabolism in autoimmune diseases and malignancies is implicated." (PMID 37993883, 2023). "TRIM21 is an E3 ubiquitin ligase associated with autoimmune diseases, and the dysregulation of TRIM21 facilitates human cancer development." (PMID 32154176, 2020). "Given the pathogenic role of dysregulated cGAS-STING signaling in autoimmune disorders, targeting TRIM21’s E3 ubiquitin ligase activity could open new avenues for developing precision therapeutics to modulate this pathway in SLE and related conditions." (PMID 40165656, 2025). "TRIM21 has been used as a diagnostic marker in autoimmune diseases for decades." (PMID 36159815, 2022). "This raises the possibility that TRIM21 may coordinate with other macrophage PRRs in a pathogenic manner to drive autoimmune disease." (PMID 31468569, 2019). "A more precise understanding of how autoantibodies interact with specific TRIM21 functional domains, and the functional outcomes of these interactions, could enhance the diagnostic specificity and prognostic relevance of anti-Ro52 antibodies in autoimmune diseases." (PMID 41383611, 2025). "Therefore, the high affinity between PRY/SPRY domain of TRIM21 and IgG may be associated with promoting the pathogenic accumulation of immune complexes formed by anti-TRIM21 autoantibodies in autoimmune diseases." (PMID 39165359, 2024). "Thus, whether and how autoantibodies access this cytoplasmic protein remains a key question for TRIM21-associated autoimmune diseases." (PMID 34552597, 2021). "The TRIM21-p62 axis represents a potential therapeutic target for attenuating pathological interferon production in STING-dependent autoimmune disorders." (PMID 40165656, 2025). "TRIM21 protein is recognized for its involvement in inflammatory processes, cancer development, and autoimmune diseases." (PMID 39890802, 2025). "Clinical observations also support a correlation between TRIM21 dysfunction and more severe phenotypes of autoimmune diseases." (PMID 41383611, 2025). "The role of TRIM21 in regulating innate immunity and its involvement in autoimmune diseases, antiviral processes, and other biological processes have been extensively studied by scholars." (PMID 39890802, 2025). "TRIM21, also known as RO52, is a common target of circulating autoantibodies in autoimmune diseases." (PMID 37066876, 2023). "Tripartite motif containing-21 (TRIM21), an E3 ubiquitin ligase, was initially found to be involved in antiviral responses and autoimmune diseases." (PMID 36159815, 2022). "Ro52/TRIM21 antibodies have also been reported in a wide variety of autoimmune diseases, although often overlapping with other autoantibodies." (PMID 22394602, 2012). "Recent data suggest that the autoantigen TRIM21 negatively regulates the development of autoimmune diseases and inflammation in autoimmune pathogenesis." (PMID 22701487, 2012). "TRIM21 is an E3 ubiquitin protein ligase belonging to the ternary motif (TRIM) protein family containing RING structures that is known to act as a major autoantigen in autoimmune diseases and plays a regulatory role in innate immune signaling." (PMID 41371168, 2025). "TRIM21 is a major autoantigen in autoimmune diseases such as SS and SLE." (PMID 41383611, 2025). "Furthermore, we evaluate the potential diagnostic and stratification value of anti-Ro52 antibodies and propose TRIM21 as a novel upstream therapeutic target to restore interferon balance in autoimmune diseases." (PMID 41383611, 2025).
autoimmune disease (continued). "Conversely, TRIM21 dysfunction may promote abnormal B cell activation and proliferation, thereby contributing to the development of autoimmune diseases." (PMID 41383611, 2025). "Generally, it is accepted that TRIM21 is involved in the occurrence and development of autoimmune diseases, and its autoantibodies have also been detected in patients with different types of autoimmune diseases." (PMID 39165359, 2024). "Research has shown that compared to monocytes, macrophages significantly express higher levels of TRIM21, indicating that it may be an important regulatory factor in macrophages’ resistance to infectious and autoimmune diseases." (PMID 39165359, 2024). "Anti-TRIM21 antibodies have also been identified in a variety of autoimmune disorders." (PMID 37180137, 2023). "Additionally, TRIM21, also known as Ro52, catalyzes K48-linked ubiquitination and the degradation of IRF3 to negatively regulate interferon production and to avoid autoimmune diseases caused by excessive immune responses." (PMID 37112854, 2023). "In addition, the expression of TRIM21 is elevated in autoimmune diseases, and TRIM21 plays an important role in immune activation during pathogen infection, but only little is known about its inherent cellular function." (PMID 35662245, 2022). "TRIM21 is mainly considered to be related to antiviral responses and autoimmune diseases." (PMID 36159815, 2022). "Of note, though, is the fact that anti-Ro52/TRIM21 antibodies are seen across a number of autoimmune diseases with significant prevalence (ranging from 1% to 63%) but are only rarely seen in normal controls; this suggests that they are markers of autoimmune dysfunction." (PMID 22394602, 2012). "TRIM21 expression has also been reported to be elevated in the brain microvasculature, which may be related to brain vascular involvement in autoimmune diseases." (PMID 22701487, 2012). "Longitudinal analysis of patients with isolated anti-Ro52/TRIM21 may be useful to establish whether this serological profile represents epiphenomena from a dysregulated immune response or is an predictive biomarker for autoimmune disease." (PMID 35871174, 2022). "Ultimately, we evaluate the feasibility of targeting TRIM21 to modulate IFN-I homeostasis and explore its prospects for clinical translation, offering new perspectives for the precision treatment of autoimmune diseases." (PMID 41383611, 2025). "Tripartite motif-containing 21 (TRIM21) plays a crucial role in antiviral responses and autoimmune diseases." (PMID 39890802, 2025). "In autoimmune diseases such as SjD, SLE, RA, and systemic sclerosis (SSc), Ro60 autoantibodies often co-exist with autoantibodies targeting Ro52 (also called TRIM21) and La/SSB." (PMID 39062948, 2024). "Furthermore, in patients with suspected autoimmune diseases, higher isolated positive serum anti-TRIM21/Ro52 antibodies are associated with a higher diagnostic rate of immunologic disorders and malignancies as compared with the anti-Ro52 and anti-Ro60 double-positive population." (PMID 37993883, 2023). "Therefore, cell surface TRIM21 might exacerbate proinflammatory pathways in autoimmune diseases." (PMID 34552597, 2021). "TRIM21 (Ro52) is a known autoantigen in IIM and related autoimmune disorders and acts as the highest-affinity Fc receptor in humans." (PMID 33772100, 2021). "Thus, TRIM21-targeted therapy may offer a useful new strategy for treating autoimmune diseases." (PMID 22701487, 2012). "Identifying the interconnected role of TRIM21/Ro52 between SLE, pSS, and tumorigenesis would be beneficial, as this could help develop an appropriate cancer monitoring method for patients with autoimmune diseases and may shed light on the disease development of SLE and pSS themselves." (PMID 37993883, 2023).
autoimmune disease (continued). "The authors found that anti-Ro52/TRIM21 antibodies were commonly found in the presence of other autoantibodies (in particular, Sm, chromatin, Jo-1, and CENP-B) and that 73% of patients had an autoimmune disease (in particular, polymyositis/dermatomyositis, SjS, SSc, and autoimmune hepatitis)." (PMID 22394602, 2012). "Studies have confirmed that TRIM21 regulates the stability and function of multiple IRF family members through ubiquitination, suggesting that it may modulate IFN-I pathway activity and contribute to the pathogenesis of autoimmune diseases by altering IRF activity." (PMID 41383611, 2025). "However, unlike their established role in autoimmune diseases, the role of anti-TRIM21 Abs in various cancers remains unclear." (PMID 40768895, 2025). "Although autoantibodies targeting TRIM21 are frequently present in the sera of patients with various autoimmune diseases, including SLE16, the actual role of TRIM21 in the pathogenesis of SLE has not been elucidated." (PMID 40610751, 2025).
myositis (91 papers, 2006 to 2026). "Anti-TRIM21 are associated with myositis autoantibodies anti-Jo-1, and accompany with positive for anti-amyl-tRNA synthetase antibody, anti-SRP or anti-PM-Scl antibody." (PMID 39165359, 2024). "The main clinical autoimmune entities associated with anti-Ro52/TRIM21 are SS, systemic sclerosis (SSc), liver autoimmune diseases, and, specially, myositis where it has been considered as an independent marker." (PMID 24294139, 2013). "It has been reported that patients with anti-TRIM21 positive ASS who are anti-Jo-1 and/or anti-PL7 positive have a significantly increased risk of concomitant ILD and exhibit more severe myositis and lower survival rates." (PMID 39165359, 2024). "Anti-Ro52/TRIM21 has also been related to a more severe disease in SS, myositis, primary biliary cirrhosis, and autoimmune hepatitis." (PMID 24294139, 2013). "Anti-Ro-52/TRIM21 is significantly more prevalent in SSc and myositis than anti-Ro-60, while isolated anti-Ro-52/TRIM21 may be found in up to 37% of patients with myositis, often in correlation with anti-Jo-1 reactivity." (PMID 26161084, 2015). "For example, a “TRIM21-interferon” module spans SjD, MDA5-myositis, and lupus nephritis; a “topoisomerase-fibrosis” module links SSc and radiation-induced fibrotic syndromes." (PMID 41562780, 2026). "A “TRIM21-interferon” module links pSS, MDA5-myositis, and lupus nephritis, while a “topoisomerase-fibrosis” module unites SSc and radiation-induced fibrotic syndromes." (PMID 41562780, 2026). "On the other hand, a negative association was observed between anti-Ro52/TRIM21 and anti-dsDNA which is consistent with the higher prevalence of this antibody in other autoimmune conditions such as SS, myositis, SSc, and liver diseases." (PMID 24294139, 2013). "Serology demonstrated the presence of anti-Ro-52/TRIM21 (high positive), but no myositis-specific, SSc-specific or SSc-overlap autoantibodies were found on line immunoassays (Euroimmun AG, Luebeck, Germany) or on Protein A-assisted immunoprecipitation using radiolabeled K562 cell extracts." (PMID 35168668, 2022).
viral infection (62 papers, 2012 to 2026). "TRIM21 was reported to be related to the imbalance of host cell homeostasis caused by viral infection." (PMID 38542289, 2024). "Animals with TRIM21 deficiency are highly susceptible to virus infection; in contrast, upregulation of TRIM21 protects mice against the virus attack." (PMID 37249651, 2023). "Collectively, extracellular stimuli, such as viral infection or TG treatment, promote the interaction between TRIM21 and PP1α, which results in K6-linked ubiquitination of PP1α." (PMID 37327222, 2023). "PKR activation commonly leads to global protein synthesis inhibition, consistent with its inhibition of PKR activation, TRIM21 reversed the global translation inhibition caused by viral infection or TG treatment." (PMID 37327222, 2023). "Our data help to clarify the biological role of TRIM21 in severe tissue pathology caused by viral infection and indicating a therapeutic target potential for TRIM21." (PMID 30410495, 2018). "Considering these observations and the interaction between vtRNA1-1 and TRIM21/25 we revealed here, it can be inferred that the regulation of vtRNA1-1 stability could also be implicated in modulating immune responses against viral infection." (PMID 40096176, 2025). "Furthermore, TRIM21-mediated K6-linked ubiquitination of PP1α was enhanced under conditions of viral infection or TG treatment." (PMID 37327222, 2023). "Importantly, in this study, we find that TRIM21-catalyzed K6-linked ubiquitination of PP1α restricts viral infection by promoting the protein synthesis of intrinsic antiviral effectors." (PMID 37327222, 2023). "TRIM21 is thought to regulate pathways associated with type I IFN response during virus infection." (PMID 35336995, 2022). "Expression of TRIM21 is enhanced under viral infection, where TRIM21 catalyzes K27-linked ubiquitination of MAVS-K325, which further recruits TBK1 to transduce innate immune signaling, which may serve as a fine-tuning mechanism to enhance innate immunity." (PMID 35795661, 2022). "It has been shown that TRIM21 plays an important role in regulating the immune response during viral infections." (PMID 40431659, 2025). "Previous research has illuminated the antiviral potency of TRIM21 in the context of various viral infections." (PMID 41341288, 2025). "The TRIM21 pathway is vital for virus infections as it has a dual function, leading opsonized viruses to degradation by proteasomes and the activation of innate inflammatory anti-virus response." (PMID 40141410, 2025). "TRIM21 acts as an antibody-binding protein in innate immune cells and functions as a cytosolic Fc receptor regulating viral infection." (PMID 38780244, 2024). "TRIM21 (also known as Ro52) has been shown to play an important role in the innate immune response, particularly during viral infections, and its expression is induced by type-I IFNs." (PMID 38977311, 2024). "The results showed that the Si-TRIM21 group significantly inhibited the accumulation of MDA in cells after virus infection." (PMID 38542289, 2024). "TRIM21 has been known as a critical regulator in the signaling pathway of type I IFNs during viral infection." (PMID 38780244, 2024). "Our findings provide new insight into the role of TRIM21 in oxidative stress and ferroptosis induced by viral infection." (PMID 38542289, 2024). "Consistently, the levels of p-PKR and p-eIF2α were also increased in HLCZ01 cells with TRIM21 knockdown upon poly (I:C) treatment or viral infection, demonstrating that TRIM21 can repress dsRNA- or virus-induced PKR signaling pathway activation." (PMID 37327222, 2023). "Since TRIM21 possesses Fc receptor and E3 ubiquitin ligase activities, numerous groups have tried to develop virus infection detection and prevention methods based on TRIM21." (PMID 36675197, 2023). "On the contrary, the interaction between TRIM21 and virus protein also can facilitate virus infection or immune escape for some viruses." (PMID 36675197, 2023).